ENSG00000299510 (novel transcript)
Gene: Long non-coding RNA gene on chromosome 7 (27,187,236 to 27,188,289, reverse strand). Ensembl gene ENSG00000299510.
Gene Ontology:
Biological process: negative regulation of gene expression